RNU6-1249P (RNA, U6 small nuclear 1249, pseudogene)
Gene: Small nuclear RNA gene on chromosome 17 (55,551,810 to 55,551,920, forward strand). Ensembl gene ENSG00000200107.
Homologues: Orthologues: chimpanzee U6 (99% identical), macaque U6 (89% identical). Paralogues in human: RNU6-820P (86% identical), RNU6-761P (85% identical), RNU6-1152P (84% identical), RNU6-12P (84% identical), RNU6-13P (84% identical), RNU6-16P (84% identical), RNU6-175P (84% identical), RNU6-25P (84% identical), RNU6-31P (84% identical), RNU6-32P (84% identical), RNU6-333P (84% identical), RNU6-41P (84% identical), and 1288 more.